GPR161 (G protein-coupled receptor 161)
Diseases named in the same sentence as GPR161 in open-access papers:
GPR161 is named in the same sentence as 37 diseases in open-access papers, as found by Europe PMC text mining. Sharing a sentence is not in itself a finding about the gene and the disease. The quoted sentences say what the papers report.
medulloblastoma (8 papers, 2020 to 2024). A malignant, invasive embryonal neoplasm arising from the cerebellum. "Neither paper attempted to assess the overall likelihood of a child with either an ELP1 or GPR161 loss-of-function variants developing medulloblastoma." (PMID 36961676, 2023). "We identified heterozygous germline mutations in the G protein-coupled receptor 161 (GPR161) gene in six patients with infant-onset medulloblastoma (median age, 1.5 years)." (PMID 31609649, 2020). "Similar to SUFU, GPR161 variants seem to be found primarily in infant medulloblastoma; previously reported in 3.4% of pediatric SHH medulloblastoma cases (5 of 6 of our reported cases were under the age of 12 months), compared to only one 10-year-old case with a P/LP GPR161 variant in our cohort." (PMID 39184053, 2024). "GPR161 has been shown to be associated with medulloblastoma and breast cancer." (PMID 37737235, 2023). "Another recent study reported a novel medulloblastoma predisposition gene in GPR161." (PMID 32056145, 2020). "Another potential medulloblastoma predisposing mutation has been reported in the gene GPR161." (PMID 32056145, 2020). "For instance, parents of neonates with a GPR161 variant can be reassured that absolute risks of medulloblastoma are very small and the increased risk may disappear after age 4 years (this will be reassuring if results are given for a 5year old) similar to SUFU and PTCH1." (PMID 36961676, 2023). "While GPR161 has been reported to drive oncogenic programs in breast cancer, it acts as a negative regulator of the HH pathway in medulloblastoma (MB), where GPR161 negatively influences MB progenitor proliferation." (PMID 37510333, 2023). "In conclusion, the absolute risk of developing childhood medulloblastoma with ELP1 and GPR161 appears low and families can be reassured particularly if these genes are found incidentally on panels." (PMID 36961676, 2023). "Recent genetic sequencing studies in large series’ of predominantly childhood medulloblastoma have implicated loss-of-function, predominantly truncating, variants in the ELP1 and GPR161 genes in causation of the MBSHH subtype specifically." (PMID 36961676, 2023). "Begemann and colleagues studied 1044 medulloblastoma cases and discovered that heterozygous germline mutations in the GPR161 gene were solely related to the SHH subgroup, accounting for 5% of the SHH subgroup neonates in their medulloblastoma cohort." (PMID 35566032, 2022). "We identified P/LP variants in four of the six medulloblastoma genes: APC, ELP1, GPR161, and SUFU." (PMID 39184053, 2024). "The implied likelihood of developing medulloblastoma for both ELP1 and particularly GPR161 are overall quite low and at or well below that of PTCH1 for which no screening in childhood for medulloblastoma is recommended." (PMID 36961676, 2023).
breast carcinoma (4 papers, 2018 to 2023). "The orphan G protein–coupled receptor 161 (GPR161) is overexpressed in breast cancer, where it promotes cell migration, proliferation, and invasion." (PMID 37071417, 2023). "For example, GPR161 is functionally expressed in breast cancer and GPRC5A in pancreatic cancer and GPR68 in the tumor microenvironment." (PMID 32039239, 2019). "With a higher detection threshold (1 FPKM), GPR161 is detected in 12 of 16 triple-negative cell lines but only 13 of 31 other breast cancer cell lines." (PMID 29872392, 2018). "Because GPR161 and IQGAP1 are both overexpressed in breast cancer, their crosstalk may participate in carcinogenesis." (PMID 37071417, 2023).
spina bifida (4 papers, 2021 to 2025). A congenital neural tube defect in which vertebrae are not fully formed. "Recently, GPR161 mutations have been reported in patients suffering from caudal neural tube defects (spina bifida)." (PMID 34346313, 2021). "While GPR161 has been previously linked with the WNT pathway and the planar cell polarity effector FUZ in spina bifida, our experiments here demonstrate that GPR161-mediated HH pathway regulation controls cranial neural tube closure." (PMID 41417007, 2025). "In particular, the closed form of spina bifida was partly due to reduced Pax3 and Cdx4 gene expression in the posterior dorsal neural tubes of Gpr161 mutant embryos with decreased Wnt signaling, whereas Shh signaling was increased." (PMID 37885410, 2023). "In detail, lineage-specific deletion of PAX3 by G protein-coupled receptor 161 (Gpr161) knockdown in mice led to cranial vault and facial bone hypoplasia, vertebral abnormalities, and the closed form of spina bifida during embryonic development, likely mediated by decreased Wnt/β-catenin signaling." (PMID 41141997, 2025).
Bardet-Biedl syndrome (2 papers, 2020 to 2022). A ciliopathy with multisystem involvement. "Interestingly, we find that two additional ciliary G protein-coupled receptors (Gpr161 and Gpr19) abnormally accumulate in cilia on Bardet-Biedl syndrome neurons." (PMID 36699005, 2022). "Patched 1, GPR161, SMO and other ciliary membrane proteins are all ferried out of cilia in a regulated manner by an evolutionarily conserved complex of eight Bardet-Biedl Syndrome (BBS) proteins, the BBSome." (PMID 32510327, 2020).
lung carcinoma (2 papers, 2024 to 2025). "Additionally, ADH1B, ZNF300, GPR161, and RDH11 were presented as the novel regulatory genes in lung injury and lung cancer." (PMID 39940682, 2025).
melanoma (2 papers, 2022 to 2026). A malignant, usually aggressive tumor composed of atypical, neoplastic melanocytes. "Together, our findings revealed that GPR161 promotes melanoma malignancy by linking STAT3 activation to TXNIP suppression and metabolic enhancement." (PMID 41834581, 2026). "Here, we identified GPR161 as an oncogenic GPCR that is significantly upregulated in melanoma and associated with poor survival in advanced-stage melanoma." (PMID 41834581, 2026). "Functional studies revealed that GPR161 promotes melanoma cell proliferation and migration, whereas its suppression attenuates these malignant phenotypes." (PMID 41834581, 2026). "Inhibition or silencing of STAT3 reduced GPR161 expression and impaired melanoma cell growth." (PMID 41834581, 2026). "This study identified GPR161 as a potential biomarker and therapeutic target in melanoma." (PMID 41834581, 2026). "The remaining five receptors (DRD2, FZD4, GPR143, GPR161, and SMO) may be of interest in the context of melanoma, but they have not been studied yet." (PMID 35158973, 2022).
triple-negative breast carcinoma (2 papers, 2018 to 2025). An invasive breast carcinoma which is negative for expression of estrogen receptor (ER), progesterone receptor (PR), and human epidermal growth factor receptor 2 (HER2). "Of note, GPR161, an orphan receptor with more than twofold increase in expression, has previously been reported to contribute to the malignant phenotype in triple-negative breast cancer." (PMID 29872392, 2018). "Our findings thus reveal a previously unknown role for GPR161 upstream of the cAMP/PKA signaling pathway, aligning with recent studies that suggest a broader function for GPR161 beyond Hedgehog signaling, notably in promoting tumor cell invasion in triple-negative breast cancer." (PMID 40737401, 2025).
adenocarcinoma of the colon (1 paper, 2020). "Her father, likewise a carrier of the GPR161 germline mutation, has died of an adenocarcinoma of the colon at age 55 years." (PMID 31609649, 2020).
Cerebellar dysplasia (1 paper, 2024). Cerebellar dysplasia (abnormal growth or development) is defined by abnormal cerebellar foliation, white matter arborization, and gray-white matter junction. "Loss of SHH pathway inhibition in neural stem cells and GCs from lack of GPR161 and SUFU, which promotes cleavage of GLI3 into the transcriptional repressor GLI3R, can lead to hyperproliferation and cerebellar dysplasia." (PMID 39137043, 2024).
cleft palate (1 paper, 2021). Cleft palate is a fissure type embryopathy that affects the soft and hard palate to varying degrees. "The results from this study also suggest a possible genetic association of GPR161 with such craniofacial defects as cleft palate, as well as encephaloceles in humans." (PMID 34887903, 2021). "In addition, encephaloceles are often observed to be associated with other human birth defects, including other NTDs, cleft palate, craniosynostosis, which are similar phenotypes to those observed in mouse models with Gpr161 cKO or Rac1 cKO." (PMID 34887903, 2021).
cystic renal disease (1 paper, 2022). "This recessive hypomorphic allele was identified in a forward genetic screen in the mouse that caused rapid cystic renal disease and the analogous mutation in human TULP3, K389I, disrupted ciliary trafficking of ARL13B, GPR161, and INPP5E." (PMID 36276950, 2022).
Encephalocele (1 paper, 2021). A neural tube defect characterized by sac-like protrusions of the brain and the membranes that cover it through openings in the skull. "The Wnt1-Cre lineage-specific deletion of Gpr161 in mice resulted in two significant phenotypes; one involves protrusive tectal defects, while the other are craniofacial skeletal defects, both of which may underlie the development of encephalocele in some fetuses." (PMID 34887903, 2021). "Our data suggests that Gpr161 cKO can serve as a mouse model for enhancing our understanding of the basic developmental biology of encephaloceles." (PMID 34887903, 2021). "We observed three major gross morphological phenotypes in Gpr161 cKO (Gpr161 f/f; Wnt1-Cre) fetuses; protrusive tectum defect, encephalocele, and craniofacial skeletal defect." (PMID 34887903, 2021). "The dorsal midbrain was enlarged by E15.5 and the brain herniation along with protruded meninges, which is the representative phenotypes in encephaloceles, was detected in the mesencephalic ventricles of Gpr161 cKO fetuses at E17.5." (PMID 34887903, 2021). "We observed up to 69% of the Gpr161 cKO fetuses had encephalocele." (PMID 34887903, 2021). "Finally, we determined that cranial neural crest derived craniofacial bone formation was significantly inhibited in Gpr161 cKO fetuses, which partly explains the development of encephalocele." (PMID 34887903, 2021). "We also observed encephalocele in ∼69% of the Gpr161 cKO fetuses at E17.5 and E18.5." (PMID 34887903, 2021).
Gorlin syndrome (1 paper, 2023). "ELP1 and GPR161 can be dismissed as candidates for Gorlin syndrome and it now also seems unlikely that GPR161 homozygotes have Pituitary Stalk Interruption Syndrome." (PMID 36961676, 2023). "Our specific screen of GPR161 in our cohort of 27 PTCH1/SUFU pathogenic variant-negative patients with Gorlin syndrome found no pathogenic or likely pathogenic variants." (PMID 36961676, 2023). "We also screened 27 PTCH1/SUFU pathogenic variant-negative patients with Gorlin syndrome for GPR161 and found no suspicious variants." (PMID 36961676, 2023). "ELP1 and GPR161 therefore join PTCH2 as potential candidate genes for Gorlin syndrome that can be dismissed on their population frequencies and, for PTCH2 and GPR161, their absence in Gorlin syndrome kindreds." (PMID 36961676, 2023). "We did not identify GPR161 in 27 PTCH1/SUFU negative Gorlin syndrome families which represent all the 27/86-(31.4%) unexplained by known genes (59 were due to PTCH1/SUFU) meaning an unexplained population frequency far lower at 0.0021% (1 in 46,400)." (PMID 36961676, 2023). "Given the population frequencies of 0.0962% for GPR161 and 0.0687% for ELP1, neither of these genes can be a cause of Gorlin syndrome with an unexplained population frequency far lower at 0.0021%." (PMID 36961676, 2023). "The suggestive features for a possible diagnosis of Gorlin syndrome in the index GPR161 patient was not backed up by information on the father, brother and two nephews who were also heterozygous." (PMID 36961676, 2023).
Hepatic fibrosis (1 paper, 2025). The presence of excessive fibrous connective tissue in the liver. "A preprint reported that METTL3 promoted the progression of hepatic fibrosis through YTHDF2-mediated silencing of GPR161 in a m6A-dependent manner." (PMID 40100806, 2025).
Hydrocephalus (1 paper, 2023). Hydrocephalus is an active distension of the ventricular system of the brain resulting from inadequate passage of CSF from its point of production within the cerebral ventricles to its point of absorption into the systemic circulation. "More recently, deletion of Gpr161 cilia-localized G-protein coupled receptor in mouse neuroepithelial cells and RGCs at early mid-gestation-induced derepression of Sonic Hedgehog (SHH) signaling, leading to hydrocephalus at birth." (PMID 36859317, 2023).
microcephaly (1 paper, 2021). A congenital or acquired developmental disorder in which the circumference of the head is smaller than normal for the person's age and sex. "The phenotypes of Gpr161 KO embryos were varied yet included malformations of the pharyngeal arches and microcephaly, along with cranial and spinal NTDs." (PMID 34887903, 2021).
microphthalmia (1 paper, 2023). Congenital or developmental anomaly in which the eyeballs are abnormally small. "With respect to craniofacial defects, we observed tectal hypertrophy, enlarged forebrain and facial defects, initially observed at E13.5, including microphthalmia/anophthalmia and microtia, some of which were phenocopied in Gpr161 cKO mice with Wnt1-Cre in our previous study." (PMID 37885410, 2023).
polymicrogyria (1 paper, 2025). A developmental brain abnormality characterized by an excessive amount of small convolutions on the surface of the brain and cognitive dysfunction. "Notably, a previous study showed that knocking out GPR161 results in periventricular heterotopia and polymicrogyria, suggesting that the absence of GPR161 disrupts neuronal migration." (PMID 40737401, 2025).
cancer (6 papers, 2018 to 2026). A tumor composed of atypical neoplastic, often pleomorphic cells that invade other tissues. "Analysis of the cancer genome atlas datasets confirmed an inverse correlation between GPR161 and TXNIP expression and showed that low TXNIP levels predicted poor overall survival." (PMID 41834581, 2026). "For six genes [ELP1, GPR161, VHL and SDHA/B/C], a clear lack of mutational constraint calls the pediatric penetrance and/or severity of associated cancers into question." (PMID 38424437, 2024).
tumor (6 papers, 2019 to 2025). "Molecular tumor profiling revealed a loss of heterozygosity at GPR161 in all affected MBSHH tumors, atypical somatic copy number landscapes, and no additional somatic driver events." (PMID 31609649, 2020). "Additional studies are needed to identify a potential broader tumor spectrum associated with germline GPR161 mutations." (PMID 31609649, 2020). "Patients with truncating germline GPR161 mutations (genomic location: 1q24.2) showed recurrent LOH of GPR161 as a second hit in the tumor." (PMID 31609649, 2020). "Analysis of tumor DNA in GPR161 germline mutation carriers revealed LOH at the GPR161 locus, unexceptionally leading to loss of the wild-type allele in all affected patients (P = .03, n = 6, binomial test)." (PMID 31609649, 2020). "However, exome-wide analysis for rare damaging germline mutations revealed a frameshift mutation in GPR161 on chromosome 1q24.2, and subsequent analysis of tumor DNA showed a somatic copy-neutral loss of heterozygosity (cnLOH) event on 1q." (PMID 31609649, 2020). "We next moved into analyzing GPR161, a Gαs-coupled receptor that is one of the primary inhibitors of Hedgehog signaling during development and tumor formation 2,27,29." (PMID 40060632, 2025). "Moreover, the lack of 1q loss events among GPR161 wild-type MBSHH tumors and the preferential mode of GPR161 inactivation, either focal or via cnLOH, suggests that 1q harbors dose-sensitive genes that might restrict MBSHH tumor development." (PMID 31609649, 2020). "We also determine that tumors arising from Gαs pathway inactivation are independent of the canonical Hedgehog regulators SMO and GPR161 and establish the Gnas-eKO and PKI models as a unique resource to understand tumor formation arising from noncanonical activation of Hedgehog signaling." (PMID 40060632, 2025).
infection (4 papers, 2010 to 2022). The state of being infected such as from the introduction of a foreign agent such as serum, vaccine, antigenic substance or organism. "During the infection of Enterotoxigenic Escherichia coli (ETEC), forkhead box O6 (FOXO6) interacts with the m6A methylase METTL3 to promote the transcription of GPR161 (encoding G protein-coupled receptor 161), which in turn regulates the expression of intestinal β-defensin." (PMID 35804542, 2022).
GPR161 also shares sentences with these, for which no sentence is quoted: pancreatic cancer (2 papers); autism (1); brain tumor (1); cervicitis (1); childhood cancer (1); CNS tumor (1); craniosynostosis (1); E. coli infection (1); genetic disorder (1); hepatocellular carcinoma (1); holoprosencephaly (1); malignant lymphoma (1); microtia (1); pituitary stalk interruption syndrome (1); squamous intraepithelial lesions (1); virus infection (1).